MTOR (mechanistic target of rapamycin kinase)
Diseases named in the same sentence as MTOR in open-access papers (continued):
Sharing a sentence is not in itself a finding about the gene and the disease.
cancer (continued). "Taking into account the anti-cancer mechanism, TQ inhibits phosphorylated mitogen-activated protein kinase (MAPK), Akt, and mammalian target of rapamycin (mTOR) involved in tumorigenesis signaling pathway." (PMID 30832444, 2019). "The other clusters in this network are related to signaling pathways of NF-kappa B, TNF, NOD-like receptor, T cell receptor, mTOR, Chemokine, MAPK, Toll-like receptor and pathways in cancer." (PMID 31776371, 2019). "By binding to the insulin receptor, insulin activates downstream AKT/mTOR/PI3K and ERK/RAS/MAPK pathways which are involved in cancer proliferation and survival." (PMID 30733504, 2019). "Depriving from the acute stimulatory effect of cancer on the FOXO machinery and mTOR inhibition in neurons, these cells will gather the accumulated oxidative damage, and higher possibility to restart a cell cycle, within the years." (PMID 30881282, 2019). "Despite the promising pre-clinical evidence, clinical trials using combined mTOR and Ras/MAPK pathway inhibition of different cancer types have had varied results." (PMID 31817676, 2019). "Breast (SKBr3 and MDA-MB-468) and colorectal (HCT8) cancer cells were treated with the pan-Akt inhibitor MK2206 and pan-mTOR inhibitor AZD8055." (PMID 30056610, 2019). "Two central cellular players involved in many paradigms of pro-survival autophagy of cancer cells are mTOR and AMPK that are often involved in activation of autophagy as an unwanted side effect of different cancer drugs/treatments." (PMID 31671879, 2019). "Sirtuin- (SIRT-3), phospho-mammalian target of rapamycin (p-mTOR) and hypoxia-inducible factor- (HIF-1α) are involved in metabolism and cancer." (PMID 30917505, 2019). "Aerobic exercise seems more powerful than anaerobic in preserving muscle from wasting during cancer, in fact, the AKT/mammalian target of rapamycin (mTOR) signaling appears even hyperactivated in muscles of cancer-bearing rodents." (PMID 31614775, 2019). "NVP-BEZ235 (dactolisib) inhibits the activity of multiple class I PI3K isoforms, mTOR and ataxia telangiectasia, and Rad3-related protein (ATR) and has potent anti-cancer activity." (PMID 31277692, 2019). "In terms of their enriched processes and functions, we observed again important pathways such as focal adhesion, mTOR signaling pathway and AMPK signaling pathway, which are also known to regulate cell cycle, and cell migration, and are critical in cancer." (PMID 30601803, 2019). "Targeted inhibition of the mTOR pathway thus can support the treatment of TNBCS, overcome resistance to chemotherapy/radiation therapy and block aggressive phenotypes in these cancers." (PMID 30626087, 2019). "Several signaling pathways are reported to be activated in cancer cells under hypoxic conditions including HIF, PI3K/Akt/mTOR, NOX, Wnt/β-catenin, and Hedgehog." (PMID 30972102, 2019). "Among agents that interfere with this signaling pathway, several inhibitors of mTOR, such as CCI-779, which is an analog of rapamycin, have demonstrated efficacy in several cancer types." (PMID 31151160, 2019). "However, many of the studied PI3K/AKT/mTOR inhibitors exhibited only modest anticancer activities in patients and/or prohibitive toxicities, and only a small number of these agents have thus far been approved for clinical treatment of a small number of selected cancers." (PMID 31058807, 2019). "These include the PI3K-Akt/mTOR (9 genes), FoxO (7 genes), Jak-STAT (7 genes), Chemokine (7 genes) and Focal adhesion (7 genes) signalling pathways and the Proteoglycans in cancer (8 genes) pathway." (PMID 31429737, 2019). "By interfering in PI3K/Akt/mTOR pathways, QUE exerts its metabolic effect on cancer, inhibiting key enzymes of glycolysis and glucose uptake." (PMID 31261749, 2019). "The mTOR pathway is known to be hyperactivated in several cancers, including HNSCC, and both mTOR complexes play essential roles in HNSCC tumorigenesis." (PMID 30970654, 2019).
cancer (continued). "A possible mechanism by which miRNA-17 promotes cancer onset and progression is enhancement of cell proliferation through modulation of the PI3K/Akt/mTOR pathway." (PMID 31244320, 2019). "The mutual antagonistic mechanism between miR-451 (mTOR) and AMPK complex and the cell’s strategic metabolic adaptation support the survival of cancer cells even in a nutrient-deprived microenvironment." (PMID 31009513, 2019). "It has been shown that the mTOR/p70S6K pathway, NF-κB pathway and MAPK pathway regulate the HIF-1 pathway during cancer progression." (PMID 31455352, 2019). "On the other hand, once exposed to the four anti-cancer drugs, the A549 cells forming ALI multilayered co-cultures showed a clear increase in the p-mTOR expression levels as compared to ALI multilayered mono-cultures exposed to the same drugs." (PMID 31464606, 2019). "Thus, the dependence of cancer cells to a specific metabolic pathway makes such a pathway a viable target for inhibition and could prove to be more effective especially when combined with mTOR inhibition." (PMID 31817676, 2019). "The mammalian target of rapamycin (mTOR), is a serine/threonine kinase of the PI3K (phosphoinositide 3-kinases)-related kinase family involve in cancer cell growth and cell survival." (PMID 31841506, 2019). "Multiple cancers exploit this pathway to confer growth advantage under limited nutrition conditions, making the PI3K/Akt/mTOR axis an attractive therapeutic target." (PMID 31192132, 2019). "Therefore, targeting epigenetic machinery may resensitize cancer cells to mTOR inhibitors." (PMID 31010254, 2019). "Tanshinone IIA, one of the main compounds of S. miltiorrhiza Bunge, has been shown to inhibit the growth of cancer cells via autophagy and apoptosis, which is related to the Beclin-1/Atg7/Atg12-Atg5 and PI3K/Akt/mTOR pathways." (PMID 31406500, 2019). "Further, mTOR also suppresses mitophagy through ATG1 dephosphorylation and inactivation in cancer cells." (PMID 31600993, 2019). "This is a critical issue common to other kinase inhibitors targeting signaling molecules expressed in both cancer and immune cells (e.g., B-Raf, AKT, mTOR inhibitors)." (PMID 31315298, 2019). "Translation is a highly regulated process that is perturbed in human cancers, often through activation of the PI3K/mTOR pathway which impacts directly on the ribosome recruitment phase of translation initiation." (PMID 30718665, 2019). "mTOR is involved in PI3K/AKT/mTOR signaling, which plays a crucial role in the pathogenesis of cancer." (PMID 31867325, 2019). "Taken together, these findings demonstrate for the first time that CASC9, which is highly expressed in cancer cells, inhibits autophagy by activating the AKT/mTOR pathway." (PMID 30674868, 2019). "PI3K/Akt/mTOR pathway is often deregulated in human cancers including GBM, and is involved in cancer stem cell maintenance, thus inducing an uncontrolled proliferation." (PMID 30845654, 2019). "The importance of PI3K in cancer is underscored by the anticancer effect of drugs that inhibit downstream effectors of PI3K/Akt signaling, such as rapamycin, an mTOR inhibitor." (PMID 31413155, 2019). "GHR inhibition decreased the activation of the AKT/mTOR and JAK/STAT pathways, which are major regulators of cancer cell proliferation and survival." (PMID 30617282, 2019). "Main regulators of the glycolytic switch observed in cancer cells involve HIF-1α, c-Myc, Akt and mTOR." (PMID 31198853, 2019). "Recent evidence indicates that the PI3K/AKT/mTOR network plays a key role for the virus/host cell crosstalk in both normoxic and hypoxic HPV-positive cancer cells." (PMID 31058807, 2019). "Quercetin exerts its anti-cancer effects on cancer cells and tumors by modulating PI3K/Akt/mTOR, Wnt/β-catenin, and MAPK/ERK1/2 pathways." (PMID 31261749, 2019). "Regarding the anti-cancer properties of metformin, it is postulated both direct effects on cancer cells, specifically through abolition of the AMPK/mTOR pathway." (PMID 31870092, 2019).
cancer (continued). "In addition, mTOR, which is a master growth regulator, promotes aerobic glycolysis and stimulates the expression of pyruvate kinase isozyme M2 (PKM2), a key glycolytic enzyme, indicating that proteins associated with the mTOR complex regulate nutrient-sensitive aerobic glycolysis in cancer cells." (PMID 31554233, 2019). "In summary, we found that vanillic acid inhibited HIF-1α by suppression of mTOR/p70S6K/4E-BP1 and Raf/MEK/ERK signaling pathways, subsequently inhibiting proliferation and angiogenesis of human cancer cells." (PMID 30678221, 2019). "Combined effects of PI3K/AKT/mTOR and PDT as a treatment regimen for cancers still needs further investigation." (PMID 31075885, 2019). "mTOR signaling is frequently upregulated in malignant tumors, including TNBC, highlighting the potential of mTOR kinase targeted therapy in cancer modulation." (PMID 31388935, 2019). "Our results are in good agreement with Liu and colleagues who described that the activation of JNK and inhibition of mTOR lead to autophagy in PANC-1 and A549 cancer cells." (PMID 31547522, 2019). "The cytotoxic effect of [Pt(O,O′-acac)(γ-acac)(DMS)] was strong compared to that observed in other cancer cell lines, due to autophagy through a mechanism mediated by JNK and PI3K/AKT/mTOR/p70S6K pathways." (PMID 30845773, 2019). "In cancer cells, AMPK activation and mTOR suppression result in both survival and proliferation failure." (PMID 30766532, 2019). "Insight into KRAS-driven CRCs will stimulate new research to find the best approach to treat this aggressive type of cancer, encouraging further evaluations of novel combination strategies including PI3K/mTOR/AKT inhibitors." (PMID 31771279, 2019). "To date, pharmacological induction of autophagy, i.e., through mTOR inhibition or AMPK activation, has been shown to have some potential in cancer prevention and therapy." (PMID 31052524, 2019). "The signalling pathways involved in the culture MultiDrug Resistance (MDR) were influenced by the cancer cell-fibroblast cross-talk, which was mediated through TGF-β1 release and subsequent activation of the PI3K/AKT/mTOR pathway." (PMID 31464606, 2019). "As key intermediates in oncogenic EGFR, MAPK, RAS/RAF/MEK/ERK and PI3K/AKT/mTOR signaling, FAM83 involved in a variety of important cancer cell signaling functions and overexpressed in many human cancers." (PMID 30910840, 2019). "Taken together, Sanhuang decoction was firstly evaluated to possess potent antibreast cancer effect in vivo through regulation of inflammation and oxidative stress accomplished by up‐regulation of Nrf2 via PI3K/AKT/mTOR signaling pathway." (PMID 31762993, 2019). "There is evidence for reciprocal regulation of AMPK and mTOR involving phospholipase D (PLD) and its metabolite in cancer cells, and it has therapeutic implications." (PMID 31766386, 2019). "The AKT- mammalian target of rapamycin (mTOR) signaling pathway is frequently co-activated along with ERK1/2 in response to growth factor signaling and in various forms of cancer." (PMID 31137762, 2019). "Previous evidence indicates participation of the Akt-mTOR pathway in activation or deactivation of the MAPK cascade, depending on cancer cell types and stimuli." (PMID 30874538, 2019). "In several cancers, including HNSCC, the expression of glucose transporter 1 (GLUT1) is often elevated, and in conjunction with enhanced mTOR signalling (mTORC1 and C2), the pair activates key oncogenic drivers, including c-MYC and HIF-1α." (PMID 30970654, 2019). "SMIs against BCL-2, IDHs, BRAF, PI3 kinase, mTOR, PARP, and CDKs have become the mainstay in the treatment of a variety of cancer types." (PMID 31807308, 2019). "This further supports the existence of cancer stem-like cell function, via both AKT2/mTOR pathway and MAPK pathway, in our resistant cell lines." (PMID 31608140, 2019).
cancer (continued). "The mTOR signaling plays a major role in promoting cell-cycle progression, and downregulation of phospho-S6RP is a feature of slow-cycling cancer cells." (PMID 31013771, 2019). "In mouse embryonic fibroblast (MEF) and a variety of human cancer cell lines, PI3K has been shown to induce Jag1 expression via the Mammalian Target Of Rapamycin Kinase (mTOR) pathway to positively regulate Notch signaling." (PMID 30716082, 2019). "Aberrant mTOR signaling promotes AKT activation leading to increased proliferation and inhibition of cell death in many cancers." (PMID 31011292, 2019). "This evidence, combined with our findings that mTOR signaling, mEAK-7, and S6K2 are upregulated in CD44+/CD90+ cancer cell populations, suggests that mEAK-7 is involved in mTOR signaling in CSCs." (PMID 31288154, 2019). "Seen as novel concepts in cancer development, ASCT2 and LAT transporters allow glutamine and EAAs to enter proliferating tumors as well as send a regulatory signal to mTOR." (PMID 30871192, 2019). "For instance, piceatannol suppresses the proliferation of cancer cells by mitochondria-mediated intrinsic pathways, including the PI3K/AKT1/mTOR, spleen tyrosine kinase, cyclooxygenase-2, and IL-6/STAT3 pathways." (PMID 31517069, 2019). "The mTOR signaling pathway is dysregulated in many forms of cancer including NSCLC and the mTOR inhibitor rapamycin decreases A549 cell proliferation, induces autophagy, and sensitizes the cells to radiation." (PMID 31231223, 2019). "Accumulated evidence has revealed that the activation of the PI3K/Akt/mTOR signaling pathway leads to the occurrence of malignant tumors, indicating that the targeted suppression of certain components in this pathway might be a potential therapeutic strategy for cancer treatment." (PMID 30897708, 2019). "Recently, several studies have shown that various transcriptional factors, such as STAT1, STAT3, BRD4, NF-kB, PI3K/AKT/mTOR, and MEK1/2/ERK1/2, promoted PD-L1 transcription in cancer cells." (PMID 31818309, 2019). "Resveratrol is also known to inhibit Akt, mammalian target of rapamycin (mTOR), PI3K as well as Wnt/catenin pathway leading to decreased cancer cell growth." (PMID 31618928, 2019). "Many early phase cancer drugs have been developed as allosteric inhibitors of mTORC1 (rapamycin and rapalogs), ATP-competitive mTOR inhibitors, or dual PI3K/mTOR inhibitors." (PMID 31878201, 2019). "The mechanism by which autophagy is induced has been widely reported, and inhibition of the AKT/mTOR, ROS/AMPK, and Bcl-2/Beclin-1 signaling pathways are known to induce autophagy in cancer cells." (PMID 30627053, 2019). "The PI3K-AKT pathway is overactivated in many human cancers, and several drugs that inhibit this pathway, including the PI3K/mTOR dual inhibitor NVP-BEZ235, are currently being tested in various preclinical and clinical trials." (PMID 31950034, 2019). "miR-223 was detected to be deregulated in cancer-related pathways, such as FOXO signaling, and in signaling pathways involved in microenvironmental mechanisms, such as hypoxia and AMPK/mTOR." (PMID 31533233, 2019). "Increasing evidence suggests the key role of metformin in cancer development and prognosis, including HCC, by exerting antineoplastic effects, primarily through mTOR inhibition in tumor cells." (PMID 30575815, 2019). "Higher concentrations of Cur induces apoptosis in cancer cells by increasing reactive oxygen species (ROS), inhibiting the PI3K/AKT/mTOR pathway and inhibiting NF-kB signaling in human neuroblastoma." (PMID 31841506, 2019). "Given the pivotal role that PI3K/AKT/MTOR plays in both ASD and cancer, we studied the differential expression status of the genes included in KEGG’s hsa04151 pathway (PI3K-Akt signaling pathway)." (PMID 31007884, 2019).
cancer (continued). "Generally, mTOR signaling regulates cell metabolism, and RCC is also a cancer of metabolism dysregulation." (PMID 30754640, 2019). "In an initial screen for tumor type sensitivity to triple PIM/PI3K/mTOR inhibition by IBL‐302, 707 cell lines derived from 47 different tumor types were tested by the Genomics of Drug Sensitivity in Cancer (GDSC) screening program." (PMID 31310053, 2019). "PIK3CA/AKT/mTOR pathway gene TSC1 (Tuberous Sclerosis 1), a known cancer driver gene in HCC21 was recurrently altered via missense mutation in one ASL and one HCC tumor in this cohort." (PMID 31796844, 2019). "In summary, our study reveals a novel signaling axis composed of mTOR, MFN2 and PKM2, which controls the metabolic switch between glycolysis and OXPHOS for cancer cell growth." (PMID 30887444, 2019). "AKT, PI3K, mTOR, p62, LC3, and Beclin 1 showed consistent downregulation of gene expressions in Lanatoside C treated cancer cells compared to untreated cells." (PMID 31783627, 2019). "Intriguingly, we observed that autophagy induction by nutrient starvation or by mTOR inhibition impairs migration and invasion of GBM cells, in line with other studies conducted on other cancer models." (PMID 30845654, 2019). "Piperlongumine, swainsonine, and sinomenine induce apoptosis and inhibit cancer cell growth through the PI3K/Akt/mTOR pathway, with decreased levels of p-Akt and p-mTOR, as evidenced by the results of Western blot analysis and immunofluorescence." (PMID 31781485, 2019). "Some studies showed that Rop inhibited cancer cells growth and survival involved in suppressing expression of cell cycle-related genes and the tranduction of PI3K/Akt/mTOR signal pathway." (PMID 31300048, 2019). "Our data has a nearly complete coverage of important cancer signaling pathways, such as shown for the PI3K/AKT/mTOR pathway, which is the primary target in targeted CRC therapy." (PMID 31805664, 2019). "PI3K/AKT/mTOR and HIF1 signaling play crucial roles in the activation of glycolysis and other cancer-related metabolic pathways, acting as bioenergetic sensors." (PMID 31366176, 2019). "Here, we show that in several cancer cell lines HF induces the AAR and concomitantly triggers the autophagy response by promoting the proteasome-mediated degradation of mTOR and the nuclear translocation of the autophagy transcription factor TFEB." (PMID 31046771, 2019). "Together, these studies establish the involvement of O-GlcNAcylation in cancer biology (increased glycolysis, proliferation, growth, and invasion) through direct activation of the PI3K/AKT/mTOR axis." (PMID 30356686, 2018). "Dysregulation of mTOR signaling pathway can be observed in many cancer cells with PI3K and AKT being upstream regulators of mTOR signaling pathway." (PMID 29533017, 2018). "Inhibition of mTORC1, an important part of mTOR pathway, leads to MAPK pathway activation through a PI3K-dependent feedback in human cancer." (PMID 30577793, 2018). "KEGG analysis surfaced that DEGs were essentially abundant in pathways in cancer, PI3K-Akt signal pathway, Jak-STAT signal pathway, TNF signaling pathway, and mTOR signaling pathway." (PMID 29854840, 2018). "Herein, we show that curcumin inhibits glucose uptake and lactate production (Warburg effect) in a variety of cancer cell lines by down-regulating PKM2 expression, via inhibition of mTOR-HIF1α axis." (PMID 29844464, 2018).